CSF1R (colony stimulating factor 1 receptor)
Diseases named in the same sentence as CSF1R in open-access papers (continued):
Sharing a sentence is not in itself a finding about the gene and the disease.
pancreatic cancer (continued). "In a pancreatic tumor mouse model, inhibition of macrophage recruitment using the CSF-1R inhibitors reduced metastatic spreading to liver, while increased macrophage conversion towards to the M2 phenotype by the loss of histidine-rich glycoprotein (HRG) increased metastatic spreading." (PMID 27191744, 2016). "For example, in patients with advanced pancreatic cancer, CSF1R inhibitors in combination with PD-1/PD-L1 inhibitors may simultaneously deregulate immune checkpoint inhibition and reduce the number of immunosuppressive macrophages, thereby enhancing the anti-tumor response of T cells." (PMID 39416792, 2024). "Furthermore, CSF1R+ macrophages contribute to pancreatic cancer growth through T cell suppression." (PMID 38643339, 2024). "It is encouraging that one clinical trial has already reported that dual PD-1 and CSF-1R blockade may provide durable clinical benefit in patients with chemotherapy-treated and immunotherapy-naïve advanced pancreatic cancer (ClinicalTrials.gov identifier: NCT02526017)." (PMID 30424804, 2018). "In pancreatic cancer models, the reprogramming of TAMs through colony-stimulating factor 1 (CSF1)/colony-stimulating factor 1 receptor (CSF-1R) blockade enhances the response to T-cell checkpoint immunotherapy." (PMID 38835055, 2024). "In another study, anti-CSF-1R significantly improved the anti-tumor effect of combined IT, consisting of anti-CTLA and anti-PD-L1, in pancreatic carcinoma models." (PMID 34205330, 2021). "Building on these results, a phase I clinical trial (NCT03153410) using the combination of IMC-CS4 (CSF1R mAb) with GVAX and anti-PD-1 is ongoing for patients with borderline resectable pancreatic cancer." (PMID 30987642, 2019). "IMC‐CS4 is a CSF1R antibody currently in phase I clinical trial in conjunction with GVAX and anti‐PD1 therapy for borderline resectable pancreatic cancer." (PMID 30003190, 2018). "In pancreatic cancer, inhibition of macrophage recruitment by targeting either the CSF-1 receptor (CSF-1R) (PLX6134, PLX3397) or CCR-2 (PF-04136309) resulted in a significant reduction of pancreatic cancer cells expressing high levels of the CSC marker ALDH." (PMID 27191744, 2016). "In tumors with abundant stromal components, such as pancreatic cancer and CRC, combining CSF-1R inhibitors with immunotherapy may be effective." (PMID 39000110, 2024). "In an experimental study in experimental pancreatic cancer on mice, the combination of anti-PD-1 with anti-CTLA-4 resulted in higher T cell infiltration and tumor response, while blocking CSF-1/CSF-1R resulted in elevated PD-1/PD-L1 expression on TAMs and increased CTLA-4 expression on CD8+ T cells." (PMID 38541123, 2024). "Notably, using macrophage Colony Stimulating Factor 1 Receptor (CSF-1R) blockers reduces TAM frequency, increases IFN production, and enhances tumor cell response to drugs in pancreatic cancer models." (PMID 38545114, 2024). "One additional pilot study is investigating the bioactivity of CSF-1R inhibitor IMC-CS4 (LY3022855) given in combination with pembrolizumab and the cyclophosphamide/GVAX anti-pancreatic cancer vaccine to patients with borderline resectable pancreatic cancer (NCT03153410)." (PMID 36077755, 2022). "In fact, the combination of the CSF-1R inhibitor cabiralizumab, the PD-1 inhibitor nivolumab, and gemcitabine failed to improve the progression-free survival of advanced pancreatic cancer patients compared to gemcitabine alone." (PMID 36143975, 2022). "A randomized phase 2b clinical trial (NCT03336216) tested the efficacy of cabiralizumab, an antibody that blocks CSF-1R, in combination with nivolumab, with or without chemotherapy, in patients with advanced pancreatic cancer." (PMID 34204306, 2021).
pancreatic cancer (continued). "Investigation of the expression of CSF1R and its ligand, CSF1, indicating that CSF1 is frequently expressed by pancreatic cancer cells whereas CSF1R expression is limited to cells in the tumor microenvironment, suggesting a tumor cell/tumor microenvironment interaction." (PMID 30003190, 2018). "In addition, macrophage depletion with clodronate and CSF1R inhibition did not provide therapeutic benefit to primary tumors in the KPC pancreatic cancer model, similar to our results." (PMID 31940491, 2020). "A range of CSF1R inhibitors are currently under clinical trials for the treatment of cancers including metastatic breast cancer (NCT01596751), ovarian cancer (NCT01525602), colorectal and pancreatic cancer (NCT02777710), solid tumors (NCT02452424) and, for rheumatoid arthritis (NCT01329991)." (PMID 31753024, 2019). "For example, a CSF1R antagonist PLX397 inhibits the infiltration of TAM into the pancreatic tumor and alters phenotype of the remaining TAM, which results in the modest suppression of the tumor growth in mice that have received orthotopic injection of syngeneic pancreatic cancer cells." (PMID 29670880, 2018). "In 2017, a promising study reported response to immunotherapy in combination of CSF-1R and PD1 antagonists in pancreatic cancer patients and is now moving on to a phase II clinical trial." (PMID 31849950, 2019).
Leukoencephalopathy (53 papers, 2015 to 2026). This term describes abnormality of the white matter of the cerebrum resulting from damage to the myelin sheaths of nerve cells. "The I794T hotspot mutation in the colony-stimulating factor 1 receptor (CSF1R) gene is associated with primary microgliopathy manifesting as leukoencephalopathy." (PMID 41763216, 2026). "Dominant-inactivating mutations in the colony stimulating factor-1 receptor (CSF1R) cause CSF-1R-related leukoencephalopathy (CRL), an adult-onset neurodegenerative disease that is modeled in the Csf1r+/- mouse." (PMID 41746753, 2026). "Another CSF1R gene mutation (c.1858+1G>T) in a family with CSF1R‐related leukoencephalopathy was located in a splicing donor site leading to exon 13 skipping from CSF1R mRNA." (PMID 38922778, 2024). "Heterozygous (Csf1r+/−) mice mimicking CSF1R‐related leukoencephalopathy symptoms due to CSF1R mutations showed cognitive and sensorimotor deficits." (PMID 38922778, 2024). "Colony‐stimulating factor 1 receptor (CSF1R)‐related leukoencephalopathy is a rare progressive neurological disease caused by heterozygous mutations in the CSF1R gene." (PMID 38922778, 2024). "To date, 17 splicing site mutations have been identified related to CSF1R‐related leukoencephalopathy." (PMID 38922778, 2024). "CSF1R gene linked leukoencephalopathy is a rare autosomal dominant inherited leukoencephalopathy characterized by increasing neuropsychiatric and motor symptoms." (PMID 39354993, 2024). "Our findings underscore the importance of intronic mis‐splicing mutations in the diagnosis and management of CSF1R‐related leukoencephalopathy." (PMID 38922778, 2024). "Nynke and colleagues reported a homozygous CSF1R splicing site mutation (c.1754‐1G>C) in a patient with pediatric‐onset leukoencephalopathy." (PMID 38922778, 2024). "Colony stimulating factor 1 receptor (CSF1R)‐related leukoencephalopathy is a rapidly progressing neurodegenerative disease caused by CSF1R gene mutations." (PMID 38922778, 2024). "In this study, we reported a novel intronic mis‐splicing mutation in the CSF1R gene associated with CSF1R‐related leukoencephalopathy." (PMID 38922778, 2024). "Subcortical ischemic vascular dementia (SIVaD), which is caused by cerebral small vessel disease, is similar to CSF1R-related leukoencephalopathy in that it mainly affects subcortical white matter." (PMID 39374256, 2024). "Approximately 95% of previously reported CSF1R variants linked to leukoencephalopathy are located within the TKD, leading to the impairment of autophosphorylation." (PMID 38922778, 2024). "Dominantly inherited mutations in colony stimulating factor 1 receptor (CSF1R) cause CSF-1R-related leukoencephalopathy (ALSP-CSFR1: CRL, OMIM # 221820)." (PMID 35683020, 2022). "Consistent with this, mutations in CSF1R can lead to leukoencephalopathy, a neurodegenerative disorder that is associated with loss of homeostatic microglia phenotype." (PMID 35481836, 2022). "CSF1R is associated with leukoencephalopathy, hereditary diffuse, with spheroids and brain abnormalities, neurodegeneration, and dysosteosclerosis." (PMID 35428183, 2022). "CSF1R-related leukoencephalopathy is an autosomal dominant neurodegenerative disease caused by mutations in the tyrosine kinase domain of the colony stimulating factor 1 receptor (CSF1R)." (PMID 35812083, 2022). "We also identified a patient with MRI brain consistent with CSF1R-related leukoencephalopathy who harbored a novel p.T567M variant of the CSF1R gene." (PMID 33597917, 2021). "Rodent models of CSF1R-related leukoencephalopathy based on Csf1r mutations have been developed and exhibit some of the human disease features." (PMID 33287883, 2020). "In support of this notion, CSF1R-related leukoencephalopathy, a disease mainly caused by CSF1R gene mutations, can lead to a marked decreased frequency of circulating non-classical monocytes during disease progression." (PMID 33203068, 2020).
Leukoencephalopathy (continued). "Neuropathological features of CSF1R-related leukoencephalopathy include a widespread loss of myelin and axons, astrogliosis and macrophage accumulation in the presence of swollen and spherical axons." (PMID 33287883, 2020). "Konno and colleagues recently proposed the diagnostic criteria for CSF1R-related leukoencephalopathy, providing ‘probable’ or ‘possible’ designations for patients without a genetic test, and yielding high sensitivity and specificity for diagnosis." (PMID 33287883, 2020). "As a genetic disease, CSF1R-related leukoencephalopathy causes emotional distress for patients and their families and poses a global burden for society." (PMID 33287883, 2020). "In CSF1R-related leukoencephalopathy, loss of Iba1+/P2ry12+ microglia were observed in vulnerable cerebral white matter, but not in unaffected grey matter." (PMID 33287883, 2020). "In this study, we identified 4 novel and 3 reported mutations in CSF1R among patients with leukoencephalopathy." (PMID 31827782, 2019). "Recently, pathogenic mutations in CSF1R were reported in a clinically and histologically similar leukoencephalopathy segregating in several families." (PMID 31775912, 2019). "In the present study, we identified 15 patients with leukoencephalopathy due to different types of CSF1R mutations." (PMID 31827782, 2019). "Variants in additional proteins associated with the TREM2 signaling pathway, SHIP1 and colony stimulating factor 1 receptor (CSF1R), have been associated with AD risk and leukoencephalopathy with spheroids." (PMID 28768545, 2017). "Therefore, comprehensive mutational analysis in patients with leukoencephalopathy is crucial for accurate genetic diagnosis and for broadening our understanding of the genetic variations associated with CSF1R-RD." (PMID 39217398, 2024). "However, ALSP linked to dominantly inherited mutations in CSF1R (colony stimulating factor receptor 1) cause CSF-1R-related leukoencephalopathy (CRP)." (PMID 35683020, 2022). "We speculate that leukoencephalopathy associated with dominant human CSF1R mutations requires an environmental trigger and/or epistatic interaction with common neurodegenerative disease-associated alleles." (PMID 35333324, 2022). "We describe the contribution of CSF1R in microglial population dynamics and neurogenesis, present an overview of genetic CSF1R variants in leukoencephalopathy, and address the pathophysiological function of microglial CSF1R in various neurodegenerative diseases." (PMID 34867307, 2021). "Moreover, elucidating the biological role of CSF1R ICD will lead to a better understanding of the underlying molecular mechanisms involved in the progress of CSF1R related leukoencephalopathy." (PMID 34867307, 2021). "Our study identified a novel p.T567M variant occurring in the juxtamembrane domain rather than the tyrosine kinase domain (TKD) of the CSF1R gene in a patient with a clinical phenotype consistent with ALSP/CSF1R-related leukoencephalopathy, classified as likely pathogenic based of ACMG criteria." (PMID 33597917, 2021). "Thus, impaired microglia are recognized as a primary causative factor underlying CSF1R-related leukoencephalopathy." (PMID 35185751, 2021). "Notably, bi-allelic and homozygous CSF1R mutations have also been recently reported in CSF1R-related leukoencephalopathy." (PMID 34867307, 2021). "Colony-stimulating factor 1 receptor (CSF1R)-related leukoencephalopathy, mainly caused by CSF1R gene mutations and regarded as the most common type of adult-onset leukoencephalopathy, currently without a cure, typically presents with progressive neuropsychiatric and motor symptoms." (PMID 33731174, 2021). "If additional factors or circulating monocytes may compensate for the loss of these tissue macrophages in CSF1R-related leukoencephalopathy requires further investigation." (PMID 33287883, 2020). "CSF1R-related leukoencephalopathy is supposed to be caused by the haploinsufficiency of csf1r gene." (PMID 33287883, 2020).
Leukoencephalopathy (continued). "While other tissue macrophages such as Langerhans cells in the skin and Kupffer cells in the liver also depend on CSF1R signaling, the effects of CSF1R mutations on these tissue macrophages in CSF1R-related leukoencephalopathy patients remains unknown." (PMID 33287883, 2020). "In order to investigate clinical and pathological characteristics of patients with CSF1R-related leukoencephalopathy and explore the potential impact of CSF1R mutations, we analyzed clinical manifestations of 15 patients from 10 unrelated families and performed brain biopsy in 2 cases." (PMID 31827782, 2019). "Due to the rarity of CSF1R‐related leukoencephalopathy, its pathogenic mechanisms remain unclear." (PMID 38922778, 2024). "These collective studies indicate that microglial activation is a primary cause of CSF1R-associated leukoencephalopathy and inhibiting microglial activation by minocycline may be an effective strategy to improve behavioral performance, based on our findings in our mouse model of ALSP." (PMID 37259140, 2023). "This case highlights early apathy and hypoactivity as red-flag manifestations of CSF1R-related leukoencephalopathy in a 42-year-old woman with rapidly progressive cognitive decline." (PMID 41647755, 2026). "This case illustrates the challenges of managing invasive fungal disease in a patient with CSF1R-related leukoencephalopathy after allo-HSCT." (PMID 41394144, 2025). "This case report details the presentation, clinical findings, and physiotherapy management of a 32-year-old female with colony-stimulating factor 1 receptor (CSF1R)-related leukoencephalopathy and a history of diabetes and hypertension." (PMID 38638743, 2024). "The haploinsufficiency can also be noted in the mouse model, with a heterozygous genotype developing CSF1R‐related leukoencephalopathy‐like symptoms." (PMID 38922778, 2024). "In this study, we identified a novel intronic mutation, c.1754‐3C > G, in the CSF1R gene within a family affected by CSF1R‐related leukoencephalopathy." (PMID 38922778, 2024). "This molecular mechanism is in line with observations in patients with CSF1R‐related leukoencephalopathy, where microglial cell numbers and dendritic arborizations are significantly reduced." (PMID 38922778, 2024). "It provides new evidence regarding differences in the patterns of WMH distribution and cortical thinning between CSF1R-related leukoencephalopathy and SIVaD." (PMID 39374256, 2024). "The consistent rise in microglial density indicates that CSF1R‐related leukoencephalopathy primarily arises from microglial abnormalities." (PMID 38922778, 2024). "Lesions in patients with CSF1R‐related leukoencephalopathy are located in the frontal and parietal lobes, periventricular, and deep white matter." (PMID 38922778, 2024). "In our pedigree, CSF1R‐related leukoencephalopathy was consistent with the dominant inheritance pattern, while one carrier (the elder sister, 5 years older than the proband) displayed no clinical symptoms yet." (PMID 38922778, 2024). "Outcome measures demonstrated significant improvements in cognitive and functional abilities, emphasizing the effectiveness of tailored rehabilitation in managing the complexities of colony-stimulating factor 1 receptor-related leukoencephalopathy." (PMID 38638743, 2024). "Further research is required to figure out the intricate interplay of these factors in determining the clinical manifestation of CSF1R‐related leukoencephalopathy." (PMID 38922778, 2024). "In both CSF1R‐related leukoencephalopathy patients and the knock‐in mouse model (Csf1rE631K/+), there is a notable reduction of microglial cell numbers and dendritic arborizations." (PMID 38922778, 2024). "The dominant negative effect and haploinsufficiency are genetic dominance forms in some CSF1R‐related leukoencephalopathy families." (PMID 38922778, 2024).